GALNT6 (polypeptide N-acetylgalactosaminyltransferase 6)
Description:
Catalyzes the initial reaction in O-linked oligosaccharide biosynthesis, the transfer of an N-acetyl-D-galactosamine residue to a serine or threonine residue on the protein receptor. May participate in synthesis of oncofetal fibronectin. Has activity toward MUC1A, MUC2, EA2 and fibronectin peptides. Glycosylates FGF23.
Synonyms: GalNAc-T6; GalNAcT6
Tractability: Antibody: UniProt predicts a signal peptide or a membrane-spanning region. PROTAC: a small molecule that binds it is known.
Target class: Enzyme; Transferase
Gene: Protein-coding gene on chromosome 12 (51,351,247 to 51,392,867, reverse strand). Ensembl gene ENSG00000139629.
Subcellular location: Golgi apparatus membrane
Subcellular location (Human Protein Atlas): Golgi apparatus; Nucleoplasm
Pathways (Reactome):
Metabolism of proteins: O-linked glycosylation of mucins
Gene Ontology:
Molecular function: polypeptide N-acetylgalactosaminyltransferase activity; protein binding
Biological process: protein O-linked glycosylation via N-acetyl-galactosamine; protein O-linked glycosylation
Cellular component: Golgi apparatus; perinuclear region of cytoplasm; Golgi membrane
Genetic constraint (gnomAD): Loss-of-function variants: 45 observed, 56.35 expected, observed/expected ratio (o/e) 0.8, 90% interval 0.63 to 1.02. The upper end of that interval is the gene's LOEUF score, 1.02, which puts it in group 4 of 6, group 1 being the genes least tolerant of losing a copy. Missense variants: 607 observed, 715.29 expected, observed/expected ratio (o/e) 0.85, 90% interval 0.79 to 0.91. Synonymous variants: 264 observed, 284.03 expected, observed/expected ratio (o/e) 0.93, 90% interval 0.84 to 1.03.
Homologues: Orthologues: chimpanzee GALNT6 (99% identical), macaque GALNT6 (98% identical), dog GALNT6 (91% identical), pig GALNT6 (90% identical), mouse Galnt6 (89% identical), rat Galnt6 (88% identical), guinea pig GALNT6 (87% identical), rabbit GALNT6 (74% identical), tropical clawed frog galnt6.3 (73% identical), Caenorhabditis elegans gly-5 (39% identical), Drosophila melanogaster Pgant5 (38% identical), Drosophila melanogaster Pgant9 (37% identical), and 10 more. Paralogues in human: GALNT3 (65% identical), GALNT4 (41% identical), GALNT13 (40% identical), GALNT12 (40% identical), GALNT1 (39% identical), GALNT2 (36% identical), GALNT11 (36% identical), GALNT16 (36% identical), GALNT14 (34% identical), GALNT5 (34% identical), GALNT10 (34% identical), GALNTL6 (34% identical), and 7 more.
Diseases named in the same sentence as GALNT6 in open-access papers:
GALNT6 is named in the same sentence as 36 diseases in open-access papers, as found by Europe PMC text mining. Sharing a sentence is not in itself a finding about the gene and the disease. The quoted sentences say what the papers report.
breast carcinoma (25 papers, 2011 to 2025). "It is necessary to identify other substrates for GALNT6, and to understand the underlying mechanism of GALNT6 in breast cancer metastasis." (PMID 38971758, 2024). "GALNT6, as one of key enzymes catalyzing the mucin-type O-glycosylation, is regarded as the most prominent breast cancer-associated GALNT." (PMID 32559179, 2020). "In this study, we found that GALNT6 was associated with poor prognosis and promoted metastasis in breast cancer." (PMID 32559179, 2020). "It is known that breast cancer expresses GALNT6 mRNA and this phenomenon is mainly associated with smaller tumours (T1)." (PMID 26161413, 2015). "In addition, GALNT6 has been reported as a diagnostic marker of breast cancer and may regulate tumorigenesis of breast cancer by modulating O‐glycosylation of fibronectin." (PMID 36409270, 2023). "Furthermore, analysis based on TCGA database which included 1043 breast cancer samples showed that enhanced GALNT6 expression was significantly associated with advanced pN stage (p = 0.033) and advanced pTNM stage (with a border line significance of p = 0.091)." (PMID 32559179, 2020). "Additionally, alterations in mucin O-glycosylation are implicated in malignant transformation of some carcinomas; GALNT6 expression has been found to be greater in breast cancer tissue compared with normal breast tissue and was correlated with venous invasion in gastric cancers." (PMID 27241529, 2016). "Multiple proteins, including mucin 1, estrogen receptor alpha, lectin galactoside‐binding soluble 3 binding protein, and α2-macroglobulin, have been identified as the substrate of GALNT6 in breast cancer." (PMID 38971758, 2024). "In breast cancer, GALNT4, GALNT6, and GALNT8, have been reported to be associated with patient outcomes, whereas no other study examines the clinical role of GALNT1." (PMID 37444599, 2023). "GALNT6 has been extensively studied for its implication in the malignant transformation and metastasis of epithelial cancers, especially in breast cancer, where it has been suggested as a novel marker for detection and a potential therapeutic target." (PMID 36553184, 2022). "GALNT6 is a member of the N-acetylgalactosyltransferase enzyme family, which exhibits oncogenic functions in several types of cancers, such as breast cancer and ovarian cancer." (PMID 35003361, 2021). "In the case of breast cancer, GALNT6 influences tumorigenicity and metastasis through the β-catenin/MUC1-C pathway." (PMID 35003361, 2021). "This study identified a new substrate of GALNT6 and provides novel understanding of the role of GALNT6 in promoting metastasis and poor prognosis in breast cancer." (PMID 32559179, 2020). "TCGA-based survival analysis and further meta-analysis of multiple studies from the SurvExpress online dataset showed GALNT6 expression was significantly positively correlated with poor OS in breast cancer." (PMID 32559179, 2020). "It is necessary to identify additional GALNT6 substrates, and to clarify the specific molecular mechanisms of GALNT6 in breast cancer metastasis." (PMID 32559179, 2020). "Search results showed that the expression of GALNT6 in breast cancer tissues was 2.139 - 7.214 fold higher than that in normal tissues in 11 out of 45 analyses (analyses refer to different analyses with multiple samples)." (PMID 32559179, 2020). "This study provides novel understanding of GALNT6 in promoting metastasis and poor prognosis of breast cancer." (PMID 32559179, 2020). "GALNT6 differential transcript expression in human breast cancer from multiple studies in the Oncomine database." (PMID 32559179, 2020). "Previous studies have reported that MUC1 and FN are classic mucin-type O-glycosylation substrates of GALNT6 which can promote the malignant phenotype of breast cancer cells." (PMID 32559179, 2020). "First, we evaluated the prognostic role of GALNT6 in invasive breast cancer in TCGA (n = 962), which is the largest one of independent breast cancer datasets in SurvExpress." (PMID 32559179, 2020).
breast carcinoma (continued). "In this study, we analyzed the effect of GALNT6 on the survival of breast cancer patients using online databases and breast cancer clinical samples, and investigated the role of GALNT6 in the migration and invasion of breast cancer cells." (PMID 32559179, 2020). "In this study, based on online database analyses and tissue microarrays, the overall survival (OS) of breast cancer patients with high expression of GALNT6 was found to be shorter than those with low expression of GALNT6." (PMID 32559179, 2020). "GALNT6 was shown to promote metastasis of breast cancer cells by enhancing mucin-type O-glycosylation, and α2M was identified as a novel substrate of GALNT6 in the secretory supernatant of breast cancer cells." (PMID 32559179, 2020). "It has been reported that the mRNA level of GALNT6 is positively correlated with bone marrow infiltration in patients with breast cancer." (PMID 32559179, 2020). "Considering the oncogenic role of GALNT6 in promoting metastasis, α2M was selected for further investigation as an important substrate in breast cancer metastasis in current study." (PMID 32559179, 2020). "SurvExpress, a web-based database prognostic analysis system, was used to evaluate the clinical significance of GALNT6 expression in breast cancer." (PMID 32559179, 2020). "Further studies are necessary to verify possible GALNT3/T6 redundancies in other cancer types, and especially in breast cancer, where GALNT6 has displayed quite similar functions in mediating aberrant O-glycosylation, as found by us for GALNT3 in EOC." (PMID 31071912, 2019). "On the level of synthesis, we observed increased protein levels of GalNT6 known to synthesize the Tn-antigen after treatment of breast cancer cells." (PMID 31455323, 2019). "In breast cancer, overexpression of N-acetylgalactosaminyltransferase (GALNT6) contributes to increased proliferation possibly through stabilization of MUC1 protein." (PMID 27754373, 2016). "In breast cancer cells, upregulation of GALNT6, a glycosyltrasferase that transfers a GalNAc residue to MUC1 protein, stabilizes MUC1 and plays a critical role in the proliferation and cytoskeletal regulation of breast cancer cells." (PMID 27754373, 2016). "Consequently, targeting GALNT6 enzymatic activity or disrupting the GALNT6/ERα interaction with membrane-permeable peptides presents a promising therapeutic approach for ERα−positive breast cancer." (PMID 40641933, 2025). "For example, GALNT6 has been shown to promote tumorigenesis and metastasis by catalyzing mucin-type O-glycosylation-mediated stabilization of MUCl and fibronectin (FN) in breast cancer cells." (PMID 38589501, 2024). "LGALS3BP may be glycosylated by GALNT6 to promote autocrine cell growth; thus, the proliferation of breast cancer cells strongly correlates with the GALNT6-LGALS3BP axis." (PMID 38393692, 2024). "We observed that GALNT6 boosted the migration and invasive ability of breast cancer cells." (PMID 38971758, 2024). "It is indicated that GALNT6 supported breast cancer cell motility through CCDC88C." (PMID 38971758, 2024). "GALNT6 was positively correlated with CCDC88C protein abundance in the normal breast and breast cancer tissues, indicating that GALNT6 might be associated with expression patterns of CCDC88C in breast cancer." (PMID 38971758, 2024). "For instance, GALNT6 was upregulated in breast cancer, and might contribute to mammary carcinogenesis through aberrant glycosylation and stabilization of MUC1." (PMID 36553184, 2022). "Furthermore, the selective expression of GALNT6 in the epithelial cells of some breast cancer patients also seems to be related to angiogenesis and invasiveness 13-15." (PMID 35003361, 2021). "In addition to this, the expression level of GALNT6 seen in breast cancer cells is substantially increased by comparison to benign, or normal breast cells." (PMID 35003361, 2021).
breast carcinoma (continued). "Our results based on the Oncomine database showed that GALNT6 was up-regulated in 11 out of 45 breast cancer analyses comparing with normal tissues, indicating that GALNT6 might play an important role in breast cancer progression." (PMID 32559179, 2020). "Subsequently, our cytology experiment confirmed that GALNT6 could promote migration and invasion of breast cancer cells." (PMID 32559179, 2020). "In addition, GALNT6-mediated mucin-type O-glycosylation can increase nuclear translocation of estrogen receptor alpha (ERα) in breast cancer." (PMID 32559179, 2020). "As α2M and CBFA2T2 showed relatively high expression, whilst AHSG and hornerin showed extremely low expression in MDA-MB-231 and MDA-MB-468 cells, we speculated that α2M and CBFA2T2 may play key roles in GALNT6-mediated metastasis of breast cancer." (PMID 32559179, 2020). "GALNT6 was shown to be able to promote the migration and invasion of breast cancer cells, and enhance the level of mucin-type O-glycosylation of substrates in the supernatants of breast cancer cells." (PMID 32559179, 2020). "However, only limited substrates of GALNT6 and their mechanisms in the development of breast cancer have been reported." (PMID 32559179, 2020). "We further validated the prognostic role of GALNT6 by IHC in breast cancer in tissue specimens." (PMID 32559179, 2020). "According to a previous study, the rate of bone marrow dissemination was 54.5% in GALNT6-positive patients, but only 4.3% in GALNT6-negative patients, suggesting that GALNT6 could be used as a biomarker of breast cancer metastasis." (PMID 32559179, 2020). "Furthermore, GALNT6 is a potential biomarker for breast cancer progression and metastasis, and an independent prognostic factor for the poor survival of gastric cancer patients." (PMID 32393740, 2020). "GALNT6 has also been shown to promote tumorigenesis and metastasis by catalyzing mucin-type O-glycosylation-mediated stabilization of MUCl and fibronectin (FN) in breast cancer cells." (PMID 32559179, 2020). "Moreover, GALNT6 exhibits analogous oncogenic functions in breast cancer (modulating aberrant O-glycosylation and MUC1 stabilization), similar to observations found by us for GALNT3 in EOC dissemination." (PMID 31071912, 2019). "GalNAcT6 (encoded by GALNT6) is expressed in the majority of breast cancers but no expression was seen in sections of normal breast tissue." (PMID 29903935, 2018). "For example, screening for GALNT6 inhibitors would be valuable for development of novel therapeutic modalities against breast cancer, since over-expression of GALNT6 might contribute to mammary carcinogenesis." (PMID 21906357, 2011). "CCDC88C also could mediate the pro-metastatic potential of GALNT6 in breast cancer." (PMID 38971758, 2024). "Moreover, CCDC88C is of importance for GALNT6 to promote breast cancer cell motility." (PMID 38971758, 2024). "Therefore, all our results clearly indicated that GALNT6 is a tumor promoter gene in breast cancer." (PMID 32559179, 2020). "Therefore, we speculated that other substrates may be involved in the GALNT6-meditated promotion of breast cancer metastasis." (PMID 32559179, 2020). "Analysis of protein abundance correlation based on the cProSite database showed that there was a positive correlation (R = 0.4431, p < 0.0001) between GALNT6 and CCDC88C protein abundance in the normal breast and breast cancer tissues." (PMID 38971758, 2024). "Analyzing glycan-related genes expression in breast cancer subtypes, GALNT3 and GALNT6 were found to be the genes that varied significantly between the five subtypes." (PMID 34830771, 2021). "In summary, our study demonstrates that GALNT6 can promote metastasis by increasing mucin-type O-glycosylation of α2M, and activating the downstream PI3K/Akt signaling pathway in breast cancer cells." (PMID 32559179, 2020). "A previous study reports that GALNT6 O-glycosylates and stabilizes Mucin 1 (MUC1), regulating the EMT process in breast cancer cells." (PMID 32393740, 2020).
breast carcinoma (continued). "GALNT6 modifies Mucin (MUC) 1 glycosylation and regulates proliferation of breast cancer cells and is essential for O-glycosylation and stabilization of MUC4 of pancreatic cells." (PMID 28388560, 2017). "In this study, we aimed at testing whether CCDC88C played a vital role in breast cancer metastasis, what was important for CCDC88C to exert its biological functions in breast cancer metastasis, and whether CCDC88C served as a substrate of GALNT6." (PMID 38971758, 2024). "Further investigation showed that GALNT6 increased O-glycosylation of α2M, and the following activation of the downstream PI3K/Akt signaling pathway was involved in the promotion of migration and invasion of breast cancer cells." (PMID 32559179, 2020). "A recent study reveals that GALNT6 O-glycosylates and stabilizes GRP78 in breast cancer cells, which may be critical for its subcellular localization and anti-apoptotic function." (PMID 32393740, 2020). "Since it has been suggested that GALNT6 could regulate breast cancer cell adhesion and growth through modification of MUC1 glycosylation and stability, we therefore tested whether GALNT6 exerted its effects via MUC1 in ovarian cancer cells." (PMID 28388560, 2017). "Furthermore, we identified α2-macroglobulin (α2M) as a GALNT6 substrate and showed that GALNT6-mediated α2M glycosylation could promote metastasis via the AKT signaling pathway in breast cancer cells." (PMID 32559179, 2020). "However, the molecular mechanism of GALNT6 in breast cancer metastasis has not been fully explored." (PMID 32559179, 2020). "We also found that some GRGs specifically associated with different tumor types are upregulated when compared to normal cells, as is the case of MUC21 in lung adenocarcinoma and GALNT6 and MUCL1 in non-TNBC breast cancer." (PMID 38384845, 2024).